CD4 (CD4 molecule)
Diseases named in the same sentence as CD4 in open-access papers (continued):
Sharing a sentence is not in itself a finding about the gene and the disease.
tumor (continued). "CD4+ T cells were sorted from tumors and tumor-draining lymph nodes of Tslp-PyMttg (test) or MMTV-PyMTtg, Tslpr(Crlf2)−/− (PyMttg TslprKO; control) mice and stimulated ex vivo using anti-CD3/CD28 antibodies plus TSLP over one to three cycles." (PMID 35657353, 2022). "In line with the findings of increased CD4+ cells in the tumor microenvironment after OV injection, it seems that anti-pathogen CD4+ memory cells play an important role in the enhancement of anticancer activity induced by OVs." (PMID 36366425, 2022). "Hot tumors with increased tumor infiltration by CD4 and CD8 T cells were observed in treated hu PDX26 mice, but not in hu PDX19 mice that expressed high levels of PD-L1." (PMID 35804867, 2022). "Fluorescence activated cell sorter (FACS) revealed an evidently increased ratio of CD8+/CD4+ T cells and apoptotic tumor cells in PDO treated with toripalimab than those treated with IgG4." (PMID 36544542, 2022). "Namely, compartmentalized tumor regions had greater densities of CD4+ T helper cells (p = 0.016), B cells (p = 0.048), antigen presenting cells (APCs) (p = 0.037), and other CD45+ immune cells (p = 0.048) than mixed tumor regions." (PMID 35217711, 2022). "When comparing skin metastases in this patient from baseline to being under IL-2 treatment, a marked increase of tumor infiltrating CD4+, CD8+ and PD-1+ T cells is seen." (PMID 35158808, 2022). "Cytotoxic enzymes can mediate direct killing of tumor cells, while production of IFNγ from NK cells as well as CD4+ and CD8+ T cells inhibits tumor growth." (PMID 35432319, 2022). "Naive B cells, memory B cells, naïve CD4 T cells and T follicular helper cells (Tfh) cells were relatively enriched in CD45 +TAS whereas CD45+ tumor had higher fractions of resting memory CD4 T cells, M1 macrophages, and M2." (PMID 36230846, 2022). "CD4+ T cells also help eliminate tumor cells through the production of IL-21 and IL-2, which are needed to adequately establish long-term memory T cells." (PMID 35267487, 2022). "We show that CD4+ T cells are sufficient to establish this tumor-suppressive phenotype, which depends on Th2 polarization and persists in the absence of CD8+ T or B cells." (PMID 35657353, 2022). "The citrullinated GRP78 189-208 and 187-206 specific CD4 responses in the mouse models were used to confirm the presence of citrullinated GRP78 in tumours and its relevance as a target for tumour therapy." (PMID 36544781, 2022). "A role for antiretroviral therapy in human immunodeficiency virus (HIV)-related EBV-SMT has been proposed; however, the relevance of tumor size, CD4 levels, and immune reconstitution inflammatory syndrome (IRIS) has not been previously reported." (PMID 35141174, 2022). "While CD8+T cells have powerful killing effects on cancer cells, CD4+T cells help CD8+ T cells priming and maturation, so CD4+ T cells must present in the tumor microenvironment for a successful antitumor response." (PMID 36793344, 2022). "CD4+ T cells can directly secrete large amounts of cytokines that kill tumor cells and inhibit tumor cell growth and proliferation." (PMID 35281908, 2022). "In the tumor infiltrate, CD4+ T cells play an important role in activating adaptive immune responses, and when reverted to an immune-suppressed state, they impair the anti-cancer immune response." (PMID 35158758, 2022). "TSC2 mRNA level was negatively correlated with the infiltration of CD8+ T cell, CD4+ T cell, regulatory T cell, dendritic cell, natural killer cell, and macrophage (tumor purity adjustment)." (PMID 35119931, 2022). "Single-cell sequencing has recently been used to identify the tumor-suppressing functions of CD4 T cells, for example, the function of GZMK+CD4+ T cells in bladder cancer." (PMID 36357424, 2022).
tumor (continued). "The proportion of CD3+ T cells was similar in all UICC stages and compared to the healthy controls, whereas the proportion of CD4+ T helper cells was progressively lower in higher tumor stages, with a statistically significant value for stage IV (** p < 0.01)." (PMID 36428793, 2022). "Recent studies have also shown that tumor-infiltrating B-cells have antitumor effects and can combine with CD4+ T-cells to enhance local immune responses." (PMID 36172179, 2022). "The frequencies of CD4+ and CD8+ T cell memory subpopulations were similar in tumor and normal tissue, except for CD4+ TTE cells, which were lower in BCP." (PMID 35562400, 2022). "As previously discussed, Vδ2+ TCRs bind to activated BTN2A1 protein sentries, bringing CD8+ and CD4+ T cells within close proximity to stressed tumor cells." (PMID 36212425, 2022). "An enhanced ratio of CD8+ CTL to CD4+ Tregs in the tumor thus constitutes an additional potential mechanistic contribution of reduced tumor growth in mice upon blockade of the A2AR and TIM3." (PMID 35013519, 2022). "It was reported that memory CD4+ T cells were related to tumor growth and the effects of chemotherapy." (PMID 35123420, 2022). "LAG3-MHC-II binding additionally recruits tumor-specific CD4+ T cells, decreasing the CD8+ T cell response." (PMID 35345849, 2022). "CD4+ T cells are members of effector T cells and have influence on infection-related diseases and tumor immunity, which can differentiate into Th17 cells and Treg cells." (PMID 36434505, 2022). "Increased CD4+ and CD8+ was found in TIL compared to PBSC in the current study, indicating that these immune cells would be more specialized and tumor-reactive tissues, caused by their exposure to tumor microenvironment." (PMID 36157879, 2022). "Studies have shown that CD4+ T cell mediated antitumor effect is closely related to inducing tumor dormancy, and tumor progression is inhibited by its independent generation of tumor necrosis factor receptor 1 (TNFR1) and interferon -γ (IFN-γ) signals." (PMID 35965504, 2022). "IHC for CD103, CD68, CD3, and CD4 was also assessed in non-tumor mice to determine the effects of RL on immune function without cancer." (PMID 35847848, 2022). "We identified that radiation therapy significantly increased the proportion of CD4+FoxP3+CD25+ T regulatory cells in the tumor following radiation therapy (RT vs. Isotype p < 0.01) (Fig. 5aiii) as has previously been described." (PMID 36056093, 2022). "BALF in the CD4/8 ratio of the past tumor group was significantly higher (8.17 + 5.19 vs. 6.08 + 4.22, p = 0.038)." (PMID 35744031, 2022). "MHC-II, i.e., major histocompatibility complex class II, has been reported to restrict CD4+ T-cell response and thus also to be relevant in tumor immunity." (PMID 36157879, 2022). "IFN-γ secreted by CD4+ Th1 cells can upregulate the expression of major histocompatibility complex Ion tumor cells and directly kill tumor cells." (PMID 35203498, 2022). "Assessment of the density of CD8+ Tdys and the proximity of CD4+ Treg to tumor cells helped to stratify patients." (PMID 36685566, 2022). "OS-ASEs have been associated with immune signatures and have been found to be positively correlated with multiple tumour-infiltrating immune cells, including CD4+ T cells and M2 macrophages." (PMID 35692800, 2022). "The highly contrasting ratio of in vitro–expanded CD4+ vs. CD8+ RepTILs between the two patients was less apparent in vivo, as tumor implants from PDX mice representing patient 16 also had a large proportion of CD4+ TILs." (PMID 35740548, 2022). "In order to better understand the heterogeneity of the CD4+ T cell subsets present in tumor‐bearing lungs, scRNA‐seq was performed." (PMID 35861366, 2022). "RFA has also been shown to increase the local infiltration of dendritic cells in the tumor, enhanced CD4+ and CD8+ T cell responses, CD45RA molecule expression by naïve T lymphocytes, and CD45RO+ memory T cell increase." (PMID 35892890, 2022).
tumor (continued). "Towards this, we determined the NFAT5 expression in the tumor-infiltrating CD4+T cells following a salt-modified diet." (PMID 35741331, 2022). "First, we calculated the distances of each macrophage, CD8+ T cell, CD4+ T cell, Treg and B cell to the nearest tumour cell or endothelial cell using the coordinates of the cell centroids." (PMID 35140207, 2022). "PD-1 is expressed on tumor-infiltrating lymphocytes (mainly CD4+ T cells), B cells, natural killer cells, monocytes and dendritic cells, while PD-L1 is highly expressed on tumor cells." (PMID 35795044, 2022). "We suggested that CD4+ T cells orchestrated comprehensive and diverse endogenous immune memory to inhibit tumor metastasis, including enhancing CD8+ CTL response, promoting NK cell activity and APC maturation." (PMID 35874660, 2022). "For example, PHLDA1 was positively correlated with the infiltration levels of a variety of immunocompetent tumor-infiltrating cells, including Act CD4, CD56dim, and Act DC and 23 types of immune promoters, including IL6, NT5E, and TNFSF9." (PMID 36142223, 2022). "This is because immunosuppressive molecules can inhibit the activation of anti-tumor cells such as CD4+ T cells and NK cells by competitively binding to epitopes of immune cells." (PMID 34998385, 2022). "The tumor-antagonizing immune cells mainly consist of NK cells, effector T cells (including effector CD4+ T cells and CD8+ cytotoxic T cells), M1-polarized macrophages and DCs." (PMID 36159787, 2022). "Through the establishment of a solid tumor model in mice, it was found that PSP+APS can significantly increase the percentage of CD3(+) and CD4(+) T lymphocytes in tumor tissues, the ratio of CD4(+)/CD8(+), and IL-2 in spleen and Bax/IL-2R expression." (PMID 35164321, 2022). "CD4 T cells that recognize an MHC class II-restricted tumor neoantigen can be identified in BCG-treated patients with NMIBC." (PMID 35804844, 2022). "In a murine lung cancer model, neoantigen-driven B cell and CD4 T follicular helper cells promoted anti-tumor immunity by enhancing CD8 T cell effector functions." (PMID 36058945, 2022). "Th1, Th2 and Th17 are part of helper T (Th) cells, which are differentiated from antigen-stimulated primitive CD4+ T cells and play different anti-tumor immune functions." (PMID 35402261, 2022). "The study revealed that PRGN-2009 treatment reduced tumor volume and increased CD8+ and CD4+ T cells in the tumor microenvironment of humanized mice bearing the human cervical tumor SiHa." (PMID 35756634, 2022). "While T-cell studies in cancer have mainly focused on CD8 T cells, given their direct tumoricidal activities and the lack of MHC class II expression in many cancer types, recent data argue for a crucial contribution of CD4 T cells to tumour immunity." (PMID 35572552, 2022). "In Ciita−/− mice, IFNα-MSCs exhibited similar ability in restraining tumor growth as WT mice, suggesting that CD4+ T cells are dispensable for the anti-tumor effect of IFNα-MSCs." (PMID 35145233, 2022). "The results showed that RFC1-5 were all positively correlated with tumor purity, negatively correlated with the infiltration of CD4+ T cell and macrophage, with significance." (PMID 35483337, 2022). "Here, we analyzed the correlation of the expression of GSTs with the level of immune infiltration of four tumor-associated immune cells: CD8+ T cells, CD4+ T cells, B cells, and Tregs." (PMID 36291099, 2022). "Together with the enhanced secretion of neo-antigens from dying tumor cells, activated DCs promote the activation of CD4+ and CD8+ T cells, monocytes and macrophages, rendering the pro-tumorigenic TME into a more anti-tumorigenic TME." (PMID 36611932, 2022). "Two months before recurrence, the frequency of tumor-specific T cells decreased, while that of IL-17 and CD4+ T cells increased." (PMID 35628206, 2022). "Specifically, Tregs were major components of CD4+ T cells and significantly accumulated in the tumor lesion across all GC patients." (PMID 35874784, 2022).
tumor (continued). "It has been shown that NRTUA treatment can elicit the expression of circulating pancreatic tumor-specific IgG in Pan02 tumor-bearing mice, and CD4+ T cells play a critical role in the re-challenge of Pan02 tumor." (PMID 36118042, 2022). "TLS with high levels of M2 macrophages and CD4+THC cells (CD3+CD8−Bcl6− ) correlates with tumor progression and a higher recurrence rate in patients with CRC." (PMID 36246629, 2022). "DCs presenting primary tumor antigens activate CD4+ CD8+ T cells in the lymph node drainage area, stimulating the expression of RANKL and IL-17F, as well as migration to the bone marrow." (PMID 36497209, 2022). "The model included an adaptive immune response, namely CD8+ cytotoxic T cells, CD4+ Th1 cells, and CD4+ Th2 cells in a 2D vascularized network grid with hypoxic and proliferating tumor regions." (PMID 36439180, 2022). "In KIRP tumor immunoassays, CD4 + T Cell, neutrophil, and macrophage expression were significantly higher in tumor tissues than in normal tissues." (PMID 36618928, 2022). "As a subgroup of CD4+ helper T cells, Treg cells can significantly restrain the tumor immune response in the human body, thus promoting tumor progression." (PMID 35342405, 2022). "For example, macrophages, CD4+ T cells, and Tregs were highly infiltrated in the tumor, while MAIT cells were mainly distributed in the adjacent liver tissues." (PMID 35347134, 2022). "The resting CD4+ T lymphocyte subclusters (C2–CD4 and C4–CD4) contained mostly cells from peripheral blood, while activated CD4+ T lymphocyte subclusters (C3–CD4 and C5–CD4) were almost exclusively populated in tumor tissues and paratumor tissues." (PMID 35562760, 2022). "The CIBERSORT scores showed that the more hypoxic tumours had increased infiltration of M0 macrophages, M1 macrophages, CD4 memory activated T cells and activated mast cells among other immune cells." (PMID 35079065, 2022). "After treatment with VVLΔTKSTCΔN1L-mIL21, the number of potent anti-tumor CD4+ and CD8+ TCMs detected in the spleen was significantly increased, an effect that was further enhanced by combining treatment with α-PD1." (PMID 35795092, 2022). "Activation of CD4 + lymphocytes with a memory phenotype enables immune cells to mount a memory response to tumor antigens, thereby preventing tumor recurrence in patients with different cancers, which is predictive of longer survival." (PMID 35123417, 2022). "Here supported by a Th-1 mediated response of CD4+ T helper cells, primed activated cytotoxic T cells recognize their cognate antigen on the surface of cancer cells leading to clonal expansion of tumour specific effector T cells." (PMID 35479076, 2022). "The result of tumor immune infiltration showed that AR was positively correlated with CD4+ T cells, macrophages, and dendritic cells, while ERBB2 was negatively correlated with CD8+ T cells, macrophages, neutrophils, and dendritic cells." (PMID 35069767, 2022). "There were significantly more CD4+ T cells in MOC1 tumor tissue from female mice compared to male mice at PID29 and PID40." (PMID 36172037, 2022). "There appears to be a decrease in the expression levels of CTLA-4 on the surface of tumour-infiltrating CD4+ T cells post-FLOT compared with the treatment-naïve setting (p = 0.07)." (PMID 35366537, 2022). "PLAG increased tumor infiltration of CD8 positive cytotoxic T-cell populations while effectively inhibiting the infiltration of neoplastic T-cells such as CD4/FoxP3." (PMID 35787261, 2022). "PD-1 was significantly upregulated on the surface of tumour-infiltrating CD4+ T cells and CD8+ T cells compared with those in peripheral circulation in the treatment-naïve setting (p = 0.003 and p = 0.007)." (PMID 35366537, 2022). "Upon transferring of naive tumor reactive CD4+ T cells into lymphopenic recipients, substantial T cell expansion and differentiation were observed." (PMID 36311701, 2022).
tumor (continued). "DCs are also associated with immunosuppression and tumor progression via the initiation of CD8+ and CD4+ T cells." (PMID 36173625, 2022). "Previous study reported that intratumor therapy with an oncolytic virus markedly inhibited tumor growth by increasing tumor infiltrated CD4+ and CD8+ T cells in a melanoma mouse model." (PMID 35762456, 2022). "In the recent years, there has been a growing body of evidence reported on significant roles of CD4+ T cells in tumor immunity." (PMID 36005179, 2022). "We have previously generated a flow cytometric analysis with representative plots and determined levels of different CD4+ T cell subsets in PBMCs, NILs, and tumor-infiltrating lymphocytes (TILs) of CRC patients." (PMID 35455287, 2022). "Similar to the Fn administration, formate treatment led to an expansion of CD4+IL-17+RORγT+ T cells in the mesenteric lymph nodes (MLNs) of formate-treated, tumour bearing mice, suggesting that the effect of Fn on Th17 cells is mediated via formate." (PMID 35437333, 2022). "Taken together, CD4+, FOXP3+, PD-L1 TILs and PD-L1 tumor cells possess the potential to predict the recurrence risk of DCIS, and the stromal PD-L1 is more valuable than the others in evaluating DCIS recurrence risk." (PMID 35843951, 2022). "Factor fork head box protein P3 (FOXP3) is always a marker of CD4 + regulatory T cells, which suppress local immunity, aid in tumor cell immune escape and promote tumor development and progression." (PMID 35654816, 2022). "Such LMP1 expressing B cells were capable to stimulate TAA specific cytotoxic CD4+ T cells and even prime such CD4+ T cell specificities from tumor patients." (PMID 35309359, 2022). "The results indicated that NCAPG2 was significantly correlated with the level of B cells, CD8+ T cells, CD4+ T cells, macrophages, neutrophils, and dendritic cells, and negatively correlated with tumor purity." (PMID 35898895, 2022). "Our data suggest that PDAC cells display functional MHC-II molecules loaded with tumor-derived peptides as PDAC cell lines induced to express MHC class II were killed by activated CD4+ T-cells." (PMID 35655709, 2022). "B cells promote the differentiation of tumor-specific CD4 Tfh cells depending on neoantigens, strengthen CD8 T-cell effector abilities by producing IL-21 and finally promote antitumor immunity." (PMID 35719407, 2022). "The expression of MHC-II on CIITA-expressing DFT cells can offer insight into the importance of CD4+ T cells in the interplay with other immune cells for anti-tumour immunity and allograft rejection." (PMID 36259237, 2022). "CD4+ T cells play a key role in the adapted immune system, which can variously target tumors either directly by eliminating tumor cells through cytolytic mechanisms or indirectly by modulating TME." (PMID 35440049, 2022). "While in the tumor positive associations between monocytic MDSC cells and CD4+ T cells are retained in both treatment groups." (PMID 35681695, 2022). "Tumor vaccines are known to generate TH1-polarised CD4 + T cells to maintain and sustain anti-tumor CD8 + CTL responses." (PMID 36316782, 2022). "Unsupervised clustering identified an effector CD8+ T cell subset (CD8+CD45ROlow) and a memory CD4+ T cell subset (CD4+CD45RO+TCF7+CD28+BTLA+TIGIT+) that were increased in posttreatment tumour specimens versus pretreatment in patients with favourable response." (PMID 36289334, 2022). "These experiments confirmed that there were significantly more CD4+ TILs per mm3 of tumor volume, but also that intratumoral penetrance was significantly enhanced in CaMKK2 KO mice." (PMID 36309495, 2022). "Tumor analysis revealed enhanced tumor infiltration of CD4+ and CD8+ T effector cells and lower numbers of CD4+Foxp3+ Treg." (PMID 35693776, 2022). "CD19+ tumor-infiltrating B-cells activated CD4+ tumor-infiltrating T-cells in the TMB of BLCA and acted as an independent prognostic factor for post-surgery survival and adjuvant chemotherapy benefits of BLCA patients." (PMID 36419891, 2022).